IL2 (interleukin 2)
Diseases named in the same sentence as IL2 in open-access papers (continued):
Sharing a sentence is not in itself a finding about the gene and the disease.
colitis (continued). "In fact, presence of B. vulgatus protects the IL-2-/- mice from developing E. coli induced colitis, which underscores that different microbes and their interactions may dictate their ability to trigger disease." (PMID 33537028, 2020). "Thus, indirubin ameliorates DSS-induced colitis by suppressing the expression of colonic TNFα, IFNγ, and IL-2 and upregulating IL-10." (PMID 32855621, 2020). "Here, we show that treatment of mice with IL-2/IL-2 antibody (JES6-1) immunocomplex during DSS-induced colitis induced Foxp3+ Treg expansion, but also potently stimulated GATA3+ type 2 innate lymphoid cell (ILC2) proliferation and high-level expression of IL-5." (PMID 30930900, 2019). "In order to explore if IL-2 delivery can induce the accumulation of Foxp3+ Treg in the colons of mice during experimental colitis, we treated wild-type C57BL/6J mice with IL-2/JES6-1 immunocomplexes beginning at the time of DSS administration (day 0) and continuing every 2 days." (PMID 30930900, 2019). "In this report, we show that treatment of mice with IL-2/JES6-1 immunocomplex during DSS-induced colitis promoted Foxp3+ Treg expansion, but also potently stimulated GATA3+ group 2 innate lymphoid cell (ILC2) proliferation and high-level expression of IL-5 in the colon." (PMID 30930900, 2019). "However, physicians administering HD IL-2 following ipilimumab should be aware of possible anti-CTLA4- related colitis exacerbation following HD IL-2 therapy since diarrhea is a common symptom with both HD IL-2 and ipilimumab treatment." (PMID 27660706, 2016). "Knockout mice for IL-2 and IL-10 spontaneously develop colitis, and it was recently documented that IL-19-deficient mice present increased susceptibility to acute DSS-induced colitis." (PMID 24718601, 2014). "Colitis development in SPF IL-2−/−-mice was characterized by a predominant Th1 response." (PMID 18545662, 2008). "The absence of colitis in B. vulgatus mpk mono-colonized IL-2−/−-mice was associated with an enhanced production of IL-6 and a decreased production of TNF-α in LP DC as compared to E. coli mpk mono-colonized mice." (PMID 18545662, 2008). "Interestingly, we found an enhanced fraction of plasmacytoid DC (pDC) in SPF IL-2−/−-mice which already suffered from colitis as well as in E. coli mpk mono-colonized mice prone to develop colitis." (PMID 18545662, 2008). "The enhanced activation of LP DC in E. coli mpk mono-colonized and SPF IL-2−/−-mice might be the consequence of a defective intestinal homeostasis in IL-2−/−-mice prone to develop colitis." (PMID 18545662, 2008). "Herein we were able to show that mono-colonization of IL-2−/−-mice with B. vulgatus mpk differentiated intestinal LP DC to a semi-mature phenotype and was associated with absence of colitis." (PMID 18545662, 2008). "Taken together these data suggest that B. vulgatus mpk induced IL-6 might account at least partially for the immune-regulatory function of B. vulgatus mpk and the prevention of colitis in B. vulgatus mpk mono-colonized IL-2−/−-mice." (PMID 18545662, 2008). "Interestingly, in IL-2−/− SPF mice already suffering from colitis we observed an increase in plasmacytoid intestinal LP DC." (PMID 18545662, 2008). "In addition, significant impairment of sodium and chloride absorption and bicarbonate secretion is found in colitis-prone IL-2-/- mice." (PMID 18680595, 2008). "The absence of colitis in B. vulgatus mpk mono-colonized IL-2−/− mice was associated with an increased expression of only IL-6 mRNA in the intestinal tissue." (PMID 18545662, 2008). "To determine whether the 83 kb Il2 enhancer contributes to auto-inflammatory disease susceptibility in vivo, we used an adoptive transfer model of IBD in which the development of colitis is determined by the balance between conventional and regulatory CD4+ T cell activities." (PMID 39302339, 2024).
colitis (continued). "EVs decreased NF-κB levels and mRNA levels of TNFα, IL-1α, IL-1β and IL-2, and increased mRNA levels of TGFβ and IL-10 in LPS-induced inflammation in human intestinal epithelial cells (HT-29) and reduce inflammation symptoms of dextran sulfate sodium-induced colitis in mice." (PMID 35432276, 2022). "Similarly, GF IL-10 deficient mice fail to develop colitis, unlike IL-2 deficient GF mice that exhibit spontaneous colitis when colonized with E. coli, but not Bacteroides vulgatus or both bacterial species together." (PMID 33147801, 2020). "Next, we investigated whether IL-2 can modulate the function of goblet cells in colitis." (PMID 32308767, 2020). "Therefore, we next explored whether IL-2/JES6-1 immunocomplexes affect colonic eosinophils during DSS-induced colitis." (PMID 30930900, 2019). "Furthermore, HBO2 treatment alone did not change the expression of proinflammatory cytokines in the colon, MLN, or spleen of the control mice; however, DSS-induced colitis resulted in a significant IL-1β and IL-6 gene upregulation in the colonic tissue and IL-2 gene upregulation in the MLN." (PMID 27656047, 2016). "From this data we conclude that the B. vulgatus triggered IL-6 secretion by LP DC in absence of proinflammatory cytokines such as IL-12 or TNF-α induces a semi-mature LP DC phenotype, which might prevent T-cell activation and thereby the induction of colitis in IL-2−/−-mice." (PMID 18545662, 2008). "Cytokines such as Th1-induced IL-2 and IFN-γ, and Th17-induced IL-17 and IL-21 promote inflammatory responses and exacerbate colitis." (PMID 40078988, 2025). "Our data revealed a significant upregulation of IL-1β, IL-2, and TNF-α levels in the colitis mice model." (PMID 38613088, 2024). "We found that the activation of Wnt/β-catenin signaling not only leads to a dramatic reduction of ILC3s but also promotes the dysfunction of ILC3s with reduced expression of IL-22, MHC-II, IL-2, GM-CSF, which further aggravates the DSS-induced colitis in mice." (PMID 38561332, 2024). "The result of our study was that the concentration of IL-2 and IL-4 was lower and the level of INF-γ and IL-17 was higher in the colon tissue of colitis mice." (PMID 37205093, 2023). "In both CD4+ and CD8+ T cells, GSEA Hallmark pathway analysis identified significant enrichment of processes such as inflammatory responses, IL2/STAT5 signalling, allograft rejection, TNF signalling and apoptosis in CPI colitis." (PMID 37872166, 2023). "Then, the following were assessed: the colitis activity score, tumor necrosis factor (TNF)-α, interleukin (IL)-2, and IL-6 serum levels, colonic length, and myeloperoxidase, malonaldehyde, and glutathione levels." (PMID 35239781, 2022). "IL-2 promoted Treg cell development via AP-1 transcription factor JunB, and injection of IL-2–anti-IL-2 antibody complex in JunBfl/fl Cd4-Cre mice expanded Treg cells and alleviated DSS-induced colitis." (PMID 35237152, 2022). "Cytokines, including IL-2, IL-6, and TNF-α, were measured in blood for cytokine profiling and to identify which cytokines best discriminate experimental colitis from controls." (PMID 35239781, 2022). "The effects of roflumilast on serum levels of TNF-α, IL-2, and IL-6 in rats with trinitrobenzenesulfonic acid (TNBS)-induced colitis (n=8)." (PMID 35239781, 2022). "Our current results indicated that rCsCP or CsCA might down-regulate the inflammatory responses of colitis mice via elevating Treg cells in both the spleens and MLNs, inducing the release of Th2 cytokines (IL-10, IL-4 and IL-13), and restraining the production of IL-1β and IL-2 cytokines in serum." (PMID 36084127, 2022). "The TNBS-induced colitis rats showed significant increases in disease activity scores, serum TNF-α, IL-2, and IL-6 levels, and colonic myeloperoxidase and malonaldehyde content." (PMID 35239781, 2022).
colitis (continued). "Quantitative analysis showed that the proinflammatory factors secreted by Th1/Th2/Th17, including IL-2, IL-6, TNF-α, IFN-γ and IL-17A significantly increased in the colitis group in both their serum and colonic tissues." (PMID 35372817, 2022). "We then employed HLA-restricted humanized mice as a pre-clinical model to assess the efficacy of LD IL-2 in IBD and found that LD IL-2 expanded human Treg cells and was protective against experimental colitis." (PMID 33717161, 2021). "Extracellular vesicles at 100 μg/mL from L. kefirgranum reduced the gene expression of IL-2, IL-8, and TNFα proinflammatory cytokines by 58, 64, and 67%, respectively, in Caco-2 cells for DSS-induced acute colitis model." (PMID 34745425, 2021). "Many of the colitis-induced cytokines that we found to be influenced by the FAAH SNP (e.g., IL-2, LIF, MCP-1, and TNF), have been found to be regulated by FAAH inhibition in other studies." (PMID 34916909, 2021). "DSS-induced colitis mice showed significant decreases in spleen and thymus indices; NK cytotoxicity; and TNF-α, IFN-γ, and IL-2 concentrations in serum." (PMID 33562018, 2021). "For IL-2 and LIF, inflammation-induced increases were reversed with an A genotype, whereas for MCP-1 and TNF, colitis-induced increases were attenuated with an A genotype." (PMID 34916909, 2021). "The production of proinflammatory mediators, including IL-1β, IL-6, TNF-α, IL-2, IL-17, and IFN-γ, plays a critical role in DSS-induced colitis in mice." (PMID 34804049, 2021). "Here we show that LD IL-2 treatment of immune humanized NSG mice induced human Treg cell expansion and was protective against experimental colitis and adds to our previous findings using HLA-restricted humanized mice." (PMID 33717161, 2021). "FAMB significantly promoted the lymphocyte proliferation and natural killer (NK) cell killing activity in colitis mice, and increased the concentrations of TNF-α, IFN-γ, and IL-2 in serum." (PMID 33562018, 2021). "Here, we show that treatment with LD IL-2 reduced 2,4,6-trinitrobenzensulfonic acid (TNBS) colitis severity in NOD.PrkdcscidIl2rg-/- (NSG) mice reconstituted with human CD34+ hematopoietic stem cells." (PMID 33717161, 2021). "Mechanistically, STAT5a, STAT5b, and STAT3 signaling, initiated by IL-2 or IL-23, respectively, in ILC3 has been shown to play a major role in Citrobacter-mediated colitis." (PMID 33435303, 2021). "Mice with DSS-induced colitis displayed reduced levels of MUC-2 expression and mucin secretion, which is restored by low-dose IL-2 treatment." (PMID 32308767, 2020). "In a mouse model of colitis, CUR treatment decreased the expression of TNF-α, IL-2, IL-6, IL-12 p40, IL-17, and IL-21 to a level comparable to healthy mice." (PMID 32423101, 2020). "In DSS-induced colitis, levels of the major pro-inflammatory cytokines including TNF-α, IL-17, and IFN-γ, were higher than those in the control and low-dose IL-2 groups (16K IU/day and 32K IU/day)." (PMID 32308767, 2020). "To examine the effect of low-dose IL-2 on inflammation-induced shortening in colon length, we evaluated the morphology of colonic inflammation in a DSS‐induced colitis mouse model." (PMID 32308767, 2020). "The gene levels associated with the common gamma chain-jak-stat pathways, which are known to be induced by IL-2, were also examined in colon tissue from DSS-induced colitis mice." (PMID 32308767, 2020). "We next examined the effects of these 4 different treatments (control IgG, IL-2/JES6-1 immunocomplexes alone, anti-IL-5 mAb alone, and IL-2/JES6-1 immunocomplexes + anti-IL-5 mAb) on DSS-induced colitis and recovery." (PMID 30930900, 2019). "Our data confirms and extends these findings by showing that administration of IL-2/JES6-1 immunocomplexes at the time of initiating DSS treatment is sufficient to expand colonic Foxp3+ Tregs and ameliorate colitis." (PMID 30930900, 2019).
colitis (continued). "In the MetS, CRC, Colitis, and other model experiments, the increase of Fecal butyrate content will reduce the expression of TNF-α, IL-2, NF-κB, and other pro-inflammatory factors." (PMID 32038285, 2019). "Toxicities observed on HD IL-2 were relatively equivalent between the groups although there were cases of CTLA4 antibody-induced colitis reported after HD IL-2 treatment and a CTLA4 antibody-induced colitis related death." (PMID 27660706, 2016). "There were significant increases on IL-2 and TNF-α levels in colon of untreated colitis mice as compared with those of the normal mice and the ERC-treated colitis mice (#p < 0.01)." (PMID 25475342, 2014). "Accordingly, the levels of the T cell cytokine IL-2 were elevated in both BALB/c C3ar-/- and B6 C3ar-/- mice after colitis induction." (PMID 23638016, 2013). "In our study, Tregs expanded by low-dose IL-2 treatment exhibited increased CLTA-4 and PD-1 in the blood and peripheral lymphoid tissues of mice with OIR or diabetic retinopathy, findings that are consistent with studies of murine atherosclerosis and colitis." (PMID 40133487, 2025). "Moreover, dietary resveratrol attenuated the inflammatory status and down-regulated the expression of proinflammatory cytokines such as IL-2, IFN-γ, IL-1β, IL-6, and TNF-α in colitis mouse model." (PMID 40078988, 2025). "In another study that utilized a DSS-induced mouse model of colitis, we found that APS could regulate the expression of inflammatory cytokines, including IL-2, IL-6, IL-12p70, IL-23 and TNF-α, in the colonic tissues of mice with colitis." (PMID 38202824, 2024). "It has been reported that IL-2 mutein can ameliorate pathological inflammation in a DSS-induced but not T-cell transfer colitis model, because IL-2Rα+CD8+ T cells exist in large amount in inflammatory lesions in the latter model." (PMID 38461332, 2024). "Therefore, we assessed the serum level of cytokines at the end of our colitis experiments, and found that IFN-γ, TNF, IL-2, IL-6, and IL-17 levels were all much higher in DSS-induced colitis mice than in control mice." (PMID 37275854, 2023). "TNBS-induced colitis rats showed significantly increased serum levels of TNF-α, IL-2, and IL-6." (PMID 35239781, 2022). "Furthermore, synthetic, disulfide-rich peptides based on ES products of A. caninum and N. americanus, reduced colitis symptoms in a TNBS model and suppressed CD4 + T cell proliferation and inhibited IL-2 and TNF production." (PMID 36186812, 2022). "However, even though the plasma level of IL-2 in our study was significantly lower in the HFD group, it only tended to increase in exercising mice treated with IAP as compared to colitis animals fed a standard diet." (PMID 35328382, 2022). "(100, 300 mg/kg) could improve the syndrome of TNBS-induced colitis mice by regulating the MPO and MDA contents and the levels of pro-inflammatory (TNF-α, IL-6, L-1β, IL-12, IFN-γ, IL-2, IL-17) cytokines and anti-inflammatory cytokines (IL-4, IL-10)." (PMID 36160392, 2022). "Altogether, those results indicate that low-dose IL-2- exerted no influence on colitis development in B27-rat." (PMID 34271972, 2021). "In addition, we revealed that the mRNA levels of IL-2 and IFNγ were mitigated by the oral administration of THF in a colitis model." (PMID 33669855, 2021). "Thus, IL-2-REH retains the ability to expand and activate Tregs in the context of an ongoing immune response, thereby improving recovery from DSS-induced colitis." (PMID 34003116, 2021). "Furthermore, possible mechanisms by which low-dose IL-2 exerted its action, as well as the detailed outcomes of such treatments were investigated in the colons of mice with DSS-induced colitis, primarily the affected sites in UC." (PMID 32308767, 2020). "In addition, we showed that low-dose IL-2 has a therapeutic effect by regulating the expression of PI3K/AKT and NF-κB in mice with DSS-induced colitis." (PMID 32308767, 2020).
colitis (continued). "IL-2 knockout mice have dysregulated T cell functions and develop chronic immune mediated colitis in SPF mice, however these mice like the IL-10-/- mice discussed earlier fail to develop colitis under germ-free conditions." (PMID 33537028, 2020). "In light of these findings, we observed that combined IL-2/JES6-1 and anti-IL-5 mAb treatment was most effective at ameliorating DSS-induced colitis compared to either treatment alone and that this regimen allowed for Foxp3+ Treg expansion without concomitant eosinophilia." (PMID 30930900, 2019). "Furthermore, IL-2/JES6-1 treatment resulted in massive eosinophil accumulation and activation in the inflamed colon, and afforded only modest protection from colitis." (PMID 30930900, 2019). "Considering that the balance of the Th17/Treg will shift to Treg cells by signals from IL‐2 and high concentration of TGF‐β, high‐dose ALA might disrupt Th17 pathway in the TNBS‐induced colitis." (PMID 31890165, 2019). "In light of these findings, we further demonstrated that combined IL-2/JES6-1 immunocomplex and anti-IL-5 mAb treatment was most effective at ameliorating DSS-induced colitis compared to either treatment alone and that this regimen allowed for Foxp3+ Treg expansion without concomitant eosinophilia." (PMID 30930900, 2019). "A previous report elegantly demonstrated that IL-2/JES6-1 immunocomplexes are effective at expanding Foxp3+ T cells in the spleens of mice and when delivered for 1 week prior to the initiation of DSS were able to lessen colitis." (PMID 30930900, 2019). "IL-2/JES6-1 immunocomplexes have been shown to induce rapid CD25+Foxp3+ Treg expansion in the spleen of mice and afford protection from dextran sodium sulfate (DSS)-induced colitis when delivered for one week prior to the initiation of DSS." (PMID 30930900, 2019). "We previously reported that CD8+CD103+ iTreg induced ex vivo with TGF-β and IL-2 potently suppressed Th cell response and Th1/Th17-mediated colitis, regardless of Foxp3 expression." (PMID 29441062, 2018). "Most HD IL-2 toxicity was not worsened by prior ipilimumab therapy except for one treatment related death from colitis." (PMID 27660706, 2016). "In the present study, PI3K and p-Akt proteins were activated in the colonic mucosa from colitis rats without treatment; in the meantime, the levels of IL-2, IL-6, IL-17, and IL-23 were increased, and the expressions of HSP70 and TGF-β were decreased." (PMID 26273312, 2015). "In animal studies, it was shown that Bacteroides vulgatus induced colitis in HLA/B27-ß2m rats, but not in IL-10−/− mice and even prevented colitis in IL-2−/− mice." (PMID 26635787, 2015). "Notably, ERCs attenuated colitis with significantly reduced DAI, decreased levels of intra-colon IL-2 and TNF-α, but increased expressions of IL-4 and IL-10." (PMID 25475342, 2014). "IL-2 deficient (IL-2−/−) mice mono-colonized with E. coli mpk develop colitis whereas IL-2−/−-mice mono-colonized with B. vulgatus mpk do not and are even protected from E. coli mpk induced colitis." (PMID 18545662, 2008). "E. coli mpk induces colitis in IL-2−/−-mice, whereas the commensal strain B. vulgatus does not and even prevents E. coli mpk induced colitis." (PMID 18545662, 2008). "B. vulgatus mpk mono-colonized mice only showed expression of IL-6 mRNA, whereas E. coli mpk mono-colonized mice, prone to develop colitis and SPF IL-2−/−-mice already suffering from colitis, revealed high levels of IL-1α, IL-1β, TNF-α, IFN-γ, IL-10 and IL-6 mRNA in the intestine." (PMID 18545662, 2008). "Animal models highlight the importance of the microbiota: genetically engineered mice lacking interleukin-2 (IL-2), interleukin-10 (IL-10), or human leucocyte antigen-B27 (HLA-B27) do not develop colitis under sterile conditions, but do so when colonised with a gut microbiota." (PMID 41356879, 2025).